SLC7A11 (solute carrier family 7 member 11)
Diseases named in the same sentence as SLC7A11 in open-access papers (continued):
Sharing a sentence is not in itself a finding about the gene and the disease.
tumor (continued). "For instance, RT-induced AMPK activation could induce the phosphorylation of Beclin 1, which could bind to the SLC7A11 module in system xc- to block cystine import and facilitate tumor cell ferroptosis." (PMID 41041050, 2025). "Upstream, transcription factors such as NRF2 (NFE2L2) and ATF4 are known to upregulate SLC7A11 transcription, conversely, the tumor suppressor BAP1 represses SLC7A11 expression via H2A deubiquitination, thereby modulating cellular susceptibility to disulfidptosis." (PMID 41185600, 2025). "While our correlative data suggest that SLC7A11 may promote immune evasion via TIDE-associated mechanisms, functional validation in immune–tumor co-culture models is needed to establish causality." (PMID 40978058, 2025). "IHC staining further demonstrated that both SDCBP2 and SLC7A11 were significantly overexpressed in tumor tissues compared with adjacent normal tissues from a total of 15 LUAD patients, and their expression exhibited a significant positive correlation (R = 0.522, P = 0.046)." (PMID 41409290, 2025). "An upregulated SLC7A11 expression in tumor cells could accumulate cystine, triggering disulfide stress, and disulfidptosis presents a new insight into the mechanisms of tumor cells." (PMID 40978058, 2025). "Moreover, extracellular cystine is preferentially taken up by tumour cells that highly express SLC7A11 but affect intratumoural CD8+ T cells function containing compromised GSH synthesis, CD36‐governed ferroptosis occur and exhausted markers expression." (PMID 40045458, 2025). "Interestingly, while SLC7A11 upregulation promotes tumor development, it also renders metastatic cancer cells more susceptible to oxidative stress, thus impeding tumor spread." (PMID 40511303, 2025). "SLC7A11 is overexpressed in various cancers, with factors stabilising or upregulating it in cells resistant to sorafenib and cisplatin, potentially reversing tumour suppression." (PMID 40916076, 2025). "A study elucidated that interferon-gamma (IFN-γ) released from CD8+ T cells can downregulate the expression levels of SLC3A2 and SLC7A11 on the tumor cell surface, thereby suppressing cystine uptake by tumor cells and ultimately promoting tumor cell lipid peroxidation and ferroptosis." (PMID 40260246, 2025). "Therefore, SLC7A11 is considered a key gene for maintaining tumor cell survival and tumor cell antioxidant defense." (PMID 40295497, 2025). "However, glucose starvation failed to induce the cleavage of caspase‐3 in these cells, indicating that neither energy stress nor apoptotic cell death is involved in the regulation of cell survival in SLC7A11‐high tumor cells upon glucose deprivation." (PMID 39739602, 2025). "Similarly, IHC results revealed that SLC7A11 expression in GBM tumors was significantly higher compared to that in adjacent non-tumor tissues." (PMID 39863603, 2025). "It inhibits the transport activity of SLC7A11, induces ferroptosis, and suppresses tumor growth." (PMID 39833180, 2025). "Intriguingly, elevated SLC7A11 expression has been reported to increase tumor cell vulnerability to disulfide stress, suggesting that activating disulfidptosis may represent a novel therapeutic strategy to overcome resistance and metastasis in OS." (PMID 41343099, 2025). "In BL, SLC7A11 expression and function may significantly influence tumor cell survival, proliferation, and therapeutic resistance." (PMID 40297144, 2025). "High expression of the cystine transporter solute carrier family 7 member 11 (SLC7A11; also known as xCT) in tumor cells leads to increased cystine uptake and the reduction of cystine to Cys, which consumes a large amount of NADPH and leads to the accumulation of disulfides in the cell." (PMID 40295497, 2025). "Additionally, direct inhibition of SLC7A11 using specific small interfering RNAs (siRNAs) has been shown to reduce PDAC tumor growth, metastasis incidence, CAF activation, and fibrosis in orthotopic mouse models of PDAC." (PMID 40427098, 2025).
tumor (continued). "Previous studies have proposed that targeting SLC7A11 or GPX4 may enhance tumor cell sensitivity to chemotherapy and radiation by inducing ferroptosis." (PMID 40113760, 2025). "Notably, tumors derived from NCI‐H2122 cells transfected with si‐SLC7A11 exhibited significantly reduced tumor volume and weight compared to control (si‐NC) groups." (PMID 41030277, 2025). "In vivo, IGF2BP3-KD suppressed tumor growth and reduced Ki67/SLC7A11 expression." (PMID 40530014, 2025). "Studies have revealed that the inhibition of SLC7A11 results in ferroptosis of tumor cells and may inhibit tumor progression, indicating that SLC7A11 is a potential therapeutic target in ferroptosis-related diseases." (PMID 40681992, 2025). "Importantly, these results highlight the feasibility of targeting SLC7A11 as a therapeutic strategy to impair tumor development in NSCLC." (PMID 41030277, 2025). "The ability of SLC7A11 to modulate cellular redox status not only influences cell survival but also impacts the efficacy of various cancer therapies, as inhibiting SLC7A11 can sensitize tumor cells to ferroptosis and enhance the effects of chemotherapy." (PMID 40535572, 2025). "For example, tumor cells with mutations in the epidermal growth factor receptor (EGFR) are more dependent on cysteine, increasing their sensitivity to the inhibition of SLC7A11 and the depletion of GSH, which induces ferroptosis." (PMID 40709182, 2025). "Tumor cells overexpressing SLC7A11 compete for cystine uptake, leaving the TME cystine-depleted." (PMID 40018041, 2025). "Moreover, IFNγ released by CD8+ T cells can down-regulate SCL3A2 and SLC7A11 in tumor cells, and promote ferroptosis." (PMID 40959280, 2025). "This, in turn, activates CD8+ T cells, triggering interferon-gamma (IFN-γ)-mediated downregulation of SLC7A11 and establishing a self-amplifying cascade of “ferroptosis-autophagy-immunity” loop that induces oxidative stress and leads to enhanced anti-tumor effects." (PMID 40963899, 2025). "Several important studies have reported that oncogenic stress can up-regulate SLC7A11 level to control the redox balance and repress ferroptosis, which could be favorable for tumor transformation and progression." (PMID 39569390, 2025). "Next, we used different energy stress inducers to treat SLC7A11‐high tumor cells and found that glutamine (Gln) starvation could induce cleavage of PARP in UMRC6 and H460 cells, and phenformin (Phe) could induce cleavage of caspase‐3 and PARP in UMRC6 cells." (PMID 39739602, 2025). "In addition, ADP-ribosylation factor (ARF) inhibits Nrf2 expression and reduces SLC7A11 expression, sensitizing tumor cells to ferroptosis." (PMID 40765833, 2025). "Crucially, we propose the therapeutic paradigm of rational combination therapy, demonstrating that USP43-high neoplasms exhibit enhanced vulnerability to synergistic tumoricidal efficacy when targeted with SLC7A11 inhibitors in concert with platinum-based agents like cisplatin." (PMID 40890129, 2025). "Additionally, IHC analysis revealed that TFR levels were increased and Ki67, GPX4, and SLC7A11 levels were decreased in shROCK2-R-QBC-939 tumours." (PMID 40615369, 2025).
tumor (continued). "In summary, the ketogenic diet led to a significant decrease in both the expression of CAV1 and SLC7A11 at the single-cell level and their overall positive rate in tumor tissues, which also significantly reduced the tumor burden through inducing ferroptosis in tumor-bearing mice." (PMID 40180904, 2025). "Consequently, SLC7A11‐high cancer cells or tumours display heightened sensitivity towards either glutamine deficiency or inhibition of key enzymes involved in glutamine metabolism." (PMID 39354653, 2025). "To explore the therapeutic application in vivo, we inoculated 7402 cells into nude mice to generate xenografts, and the results show that treatment with BAY‐876 decreased the growth of 7402 xenograft tumors, indicating that SLC7A11‐high tumor cells are sensitive to glucose inhibition." (PMID 39739602, 2025). "However, about 30% of tumor cells escape ferroptosis through SLC7A11 overexpression, leading to the failure of immunotherapy." (PMID 40535125, 2025). "We combined the mean fluorescence intensity (MFI) values from the local scan areas with clinical data to evaluate whether the expression levels of NRF2, NQO1, and SLC7A11 varied significantly across different grades and tumor-node-metastasis (TNM) stages." (PMID 40007539, 2025). "Furthermore, research has revealed that interferon-γ (IFN-γ) secreted by NK cells can significantly downregulate the mRNA and protein expression levels of SLC3A2 and SLC7A11, thus inducing ferroptosis in tumor cells." (PMID 40260246, 2025). "Moreover, SLC7A11-positive expression is correlated with microvascular invasion, reduced differentiation, and elevated tumor nodular metastasis classification." (PMID 40860678, 2025). "Similarly, targeting SLC7A11 (xCT) with sulfasalazine or siRNA-loaded nanoparticles inhibited tumor progression and remodeled the tumor microenvironment by limiting cystine uptake and redox buffering." (PMID 40282424, 2025). "HG106 inhibited SLC7A11 expression and tumor growth, especially in KRAS mutant LUAD61." (PMID 40765833, 2025). "The suppressive role of CAP on GPX4, FSP1 and SLC7A11 were confirmed using mice tumor samples." (PMID 39781456, 2025). "Moreover, this study linked two well-established tumor drivers, PTBP1 and SLC7A11, through the post-transcriptional regulation of SLC7A11 by PTBP1." (PMID 41313521, 2025). "The inhibition of SLC7A11 has been shown to induce ferroptosis in tumor cells." (PMID 40007539, 2025). "To verify whether ferroptosis also occurred in our animal experiments, we examined the mRNA and protein expression of Slc7a11 and Gpx4 genes in the tumour tissues." (PMID 41451920, 2025). "Notably, combining NSC48160 with the SLC7A11 inhibitor HG106 achieved synergistic tumor suppression, suggesting a paradigm for co‐targeting oncogenic signaling and ferroptosis vulnerability." (PMID 40390765, 2025). "Studies have shown that GPX4 and SLC7A11 are central factors in suppressing lipid peroxidation; their high expression significantly enhances the antioxidant capacity of tumor cells, enabling them to evade ferroptosis induced by immunotherapy, chemotherapy, or radiotherapy." (PMID 40416987, 2025). "However, recent contrary findings uncovered that increased SLC7A11 expression unexpectedly induced the sensitivity of tumor cells to oxidative stress, resulting in elevated rates of tumor cell apoptosis." (PMID 40765833, 2025). "Overexpressed SLC7A11 promoted tumor aggressiveness and suppressed the ferroptosis of NSCLC cells." (PMID 40417819, 2025). "Additionally, ALKBH5 was prominently downregulated in NSCLC patients, and its upregulation has been shown to inhibit tumor progression by promoting ferroptosis through the suppression of SLC7A11 expression." (PMID 40427734, 2025). "We previously identified that IFNγ could sensitize tumor cells to ferroptosis by down-regulating the expression of SLC7A11." (PMID 40645933, 2025).
tumor (continued). "(2024) highlighted the regulatory role of ferroptosis in EMT-driven tumor resistance and emphasized the importance of GPX4 and SLC7A11—mirroring our clustering results that identified “tumor microenvironment”, “resistance”, and these regulators as prominent themes." (PMID 40416987, 2025). "Despite challenges such as normal tissue toxicity and tumor heterogeneity, precise regulation of SLC7A11 has become a key direction for overcoming treatment resistance, enhancing sensitivity to ferroptosis, and optimizing metabolic-immune combination therapies." (PMID 40535572, 2025). "BAP1 induces ferroptosis in tumor cells by downregulating SLC7A11 expression." (PMID 40822852, 2025). "IFN-γ released from CD8+ T cells downregulates SLC7A11, sensitizing tumor cells to ferroptosis." (PMID 41294853, 2025). "In addition, NFE2L1 was recently shown to suppress ferroptosis in OSCC by transcriptionally upregulating HJURP, which stabilizes GPX4 and SLC7A11 expression and reduces lipid ROS accumulation, thereby promoting tumor growth and ferroptosis resistance." (PMID 41227330, 2025). "The results demonstrated that the protein and mRNA levels of NFE2L1 and GPX4 were significantly increased in tumor tissues, whereas the ferroptosis marker proteins PTGS2, and CHAC1 were expressed at low levels in tumor tissues, however, SLC7A11 exhibited significant overexpression in tumor tissues." (PMID 41189569, 2025). "Importantly, treatment with BEVs‐LCTP‐siSLC7A11 not only impaired tumorigenesis but also activated ferroptosis pathways, as evidenced by altered expression levels of SLC7A11 and transferrin in tumor and metastatic tissues." (PMID 41030277, 2025). "After describing the individual roles of the ferroptosis-related genes (G6PD, KIF20A, EZH2, NT5DC2, SLC7A11), it is essential to investigate how these genes might interact with each other to influence the tumor microenvironment (TME) in a synergistic manner." (PMID 40465746, 2025). "However, research has predominantly concentrated on the antioxidant and anti‐ferroptotic roles of SLC7A11 in tumor cells, with its function in immune cells within the TME remaining elusive." (PMID 39742309, 2024). "Human tumor-associated mutations in BAP1 do not inhibit the expression of SLC7A11 and do not suppress tumors via promoting ferroptosis." (PMID 38267442, 2024). "For example, in anti-PD-L1 immunotherapy, IFN-γ secreted by activated CD8+ T cells downregulates the expression of SLC3A2 and SLC7A11, impairs the uptake of cystine by tumour cells, and consequently promotes ferroptosis-specific lipid peroxidation in tumour cells." (PMID 38993573, 2024). "Moreover, tumor metastasis was markedly reduced in vivo by sulfasalazine, an inhibitor of SLC7A11 function." (PMID 39061826, 2024). "SLC7A11, a member of the amino acid transporter SLC7 family, is induced by IL‐1β to upregulate PD‐L1 and CSF1 through αKG/HIF1α axis, leading to infiltration of tumor‐associated macrophages and myeloid‐derived suppressor cells and promoting metastasis of HCC." (PMID 39041652, 2024). "Thus, Se-Met enables the functional coupling between SLC38A5 and SLC7A11 and this crosstalk between the two transporters forms an integral part of the antioxidant machinery in tumor cells." (PMID 38539825, 2024). "High SLC7A11 mRNA expression was associated with high tumor grade (p = .01) but not with tumor size or nodal stage." (PMID 38073087, 2024). "Moreover, radiotherapy and IFN-γ achieved synergistic effects via the inhibition of SLC7A11 to enhance lipid oxidation in tumor cells." (PMID 39043653, 2024).
tumor (continued). "SLC7A11, served as a key target for regulating ferroptosis, plays a crucial role in maintaining redox homeostasis and defending against lipid peroxidation injury during tumor progression." (PMID 39543094, 2024). "SLC7A11, a critical ferroptosis regulator and tumor promoter, was screened out." (PMID 38610018, 2024). "While long-standing research on IDO has focused on its ability to deplete Trp for immunosuppressive effects, Peter J Murray’s team discovered a new mechanism by which IDO promoted tumor development by transporting the IDO metabolite Kyn into cells via SLC7A11 and inhibiting ferroptosis in the tumor." (PMID 38755125, 2024). "Finally, we validated in vivo that the inhibition of KCNA1 in cells led to tumor suppression during intracranial growth, extended survival time in mice, and reduced the expression of SLC7A11." (PMID 38172959, 2024). "Notably, a negative correlation was observed between tumor SLC7A11 expression and T-cell infiltration, while SLC7A11 expression was positively associated with immunosuppressive Th2 infiltrates, suggesting that elevated cystine uptake by tumor cells might hamper the anti-tumor immunity." (PMID 38360744, 2024). "The study also showed that glucose transport inhibitors could induce disulfidptosis in SLC7A11 high-expression cancer cells, thus suppressing tumour growth." (PMID 39590840, 2024). "The cystine transporter SLC7A11 plays a pivotal role in tumor growth promotion." (PMID 39362848, 2024). "CRC cells with SLC7A11 low expression may more adaptive to the hypoxic tumor microenvironment and have more malignant phenotypes." (PMID 38774759, 2024). "Furthermore, the increased FXR expression was positively correlated with vimentin and SLC7A11 in clinical tumor specimens." (PMID 39543094, 2024). "Notably, silencing miR-485-3p in MIA PaCa-2 and PANC-1 cells led to an increase in tumor cell sphere formation, while knockdown of SLC7A11 reversed this effect." (PMID 38811540, 2024). "The changes in SLC7A11 molecules are highly likely to be the molecular pathological basis behind radiomics, and may show great potential in tumor treatment." (PMID 39350768, 2024). "Importantly, either Slc7a11 deletion in tumor cells or intratumoral cystine supplementation improves T cell anti-tumor immunity." (PMID 38360744, 2024). "Extensive in vitro and in vivo experiments were carried out to determine the role of ERO1α and its downstream target, member 11 of the solute carrier family 7 (SLC7A11), in mTORC1-mediated cell proliferation, angiogenesis, ferroptosis resistance, and tumor growth." (PMID 38610018, 2024). "For instance, using small interfering RNAs (siRNAs) or short hairpin RNAs (shRNA) to downregulate GPX4 or SLC7A11 could sensitize tumor cells to ferroptosis and inhibit tumor growth." (PMID 39624080, 2024). "This raises the possibility that activation of BACH1 by the Keto diet may suppress tumor growth through the down-regulation of SLC7A11 and the activation of ferroptosis." (PMID 38838145, 2024). "However, its broader implications have become evident, including the induction of ferroptosis via SLC7A11 inhibition, stimulation of apoptosis, attenuation of angiogenesis, and inhibition of tumor cell proliferation." (PMID 39516467, 2024). "Whether SLC7A11 could independently influence tumor progression and TME modulation by disulfidptosis needs to be further investigated." (PMID 38694875, 2024).